AIM2 (absent in melanoma 2)
Diseases named in the same sentence as AIM2 in open-access papers (continued):
Sharing a sentence is not in itself a finding about the gene and the disease.
tumor (continued). "Moreover, clinical data analysis showed that loss of AIM2 significantly correlated with tumor size, depth of invasion, LNM and TNM stage in patients suffering from CRC." (PMID 33291082, 2020). "Thus it indicated that innate immune DNA sensor AIM2 was implicated as a potential tumor suppressor, whereas its mechanism is not fully understood." (PMID 27167192, 2016). "Research has shown that activation of the AIM2 inflammasome in nasopharyngeal carcinoma leads to increased secretion of tumor-derived IL-1β, resulting in the recruitment of a significant population of tumor-associated neutrophils (TANs) and suppression of tumor growth in murine models." (PMID 39744568, 2025). "We speculate that both BCL2A1 and AIM2 are implicated in the tumor proliferation of PSCC." (PMID 33391539, 2021). "Therefore, with the advantages of the molecular classifiers BCL2A1 and AIM2, we identified a small proportion of pN0 patients (17.6%, 19/108) at high risk of tumor progression and poor outcomes, a subset that was imperceptible by conventional pT or G stratification." (PMID 33391539, 2021). "Additionally, OAd.TNFa-IL2 may induce antitumor effects through trough AIM2 activated, gasdermin-induced cell killing, with associated immunogenic tumor microenvironment modulation." (PMID 32225009, 2020). "StromalScore analysis suggested that NLRP3 and AIM2 were activated by the tumor immune microenvironment in KIRC." (PMID 41808837, 2026). "Accumulating evidence indicates that the AIM2 inflammasome influences tumor progression via multiple concurrent mechanisms, one of which involves the negative regulation of STING-dependent type I interferon signaling." (PMID 41811896, 2026). "In this context, the role of AIM2 in cancer is still controversial in that some authors assume that AIM2 activation has pro-tumor activities, while others define it as anti-tumor." (PMID 40002808, 2025). "AIM2 overexpression has been shown to increase tumor growth and invasion into lymphatic vessels by promoting EMT that is a critical process for cancer metastasis, which lead to decreased survival rates in affected individuals." (PMID 40386782, 2025). "The expression of AIM2 has been shown to increase the number of sub-G1 phase cells and induce apoptosis in tumor cells, effectively inhibiting BC cell proliferation, and growth in vitro, as well as suppressing breast tumor formation in vivo." (PMID 39744568, 2025). "In the therapeutic realm, radiofrequency ablation (RFA) has demonstrated efficacy inhibit HCC tumor growth by harnessing the AIM2-mediated induction of pyroptosis, a lytic form of programmed cell death." (PMID 40386782, 2025). "Mechanistically, AIM2 interacts with and restricts the activation of DNA-dependent protein kinase (DNA-PK), thereby inhibiting Akt activation and ultimately reducing tumor burden in the CRC model." (PMID 39744568, 2025). "This study illustrated the lack of AIM2 expression in healthy melanocytes and reported a reverse tumorigenic phenotype upon AIM2 overexpression in melanocytes, which prevented tumour formation." (PMID 41440367, 2025). "C–C Motif Chemokine Ligand 19 (CCL19) is a chemokine, and its upregulation inhibits GC cell proliferation and tumor growth by upregulating the C–C Motif Chemokine Receptor 7 (CCR7)/AIM2 axis, while silencing AIM2 abrogates the effects of CCL19 on tumor growth." (PMID 41291696, 2025). "Chemotherapeutic agents or cytotoxic drugs used in cancer treatment activate AIM2 by inducing tumour cell death and release of endogenous DAMPs such as ATP, HMGB, and self-dsDNA." (PMID 41440367, 2025). "Overall, AIM2 plays a significant role in tumor progression and immune regulation, making it a key target for therapeutic intervention." (PMID 40692785, 2025). "AIM2 exerts pro-tumor effects activated by STAT1/NF-κB transcription through the IL-17/MAPK pathway." (PMID 40386782, 2025).
tumor (continued). "In BRAF-mutant CRC, restoring AIM2 expression significantly inhibited tumor growth and induced necrotic cell death in a caspase-1 dependent manner, further underscoring its role as a tumor suppressor." (PMID 40386782, 2025). "First, AIM2-targeted therapy necessitates exceptionally high specificity to prevent unintended modulation of AIM2 activity in non-tumor tissues." (PMID 39744568, 2025). "Futhermore, in vivo experiments involving the transfer of AIM2-overexpressing cancer cells into immunodeficient mice revealed accelerated tumor growth in the tongue and reduced survival rates among the mice." (PMID 39744568, 2025). "In support, the blockade of IL-1β in a mouse model of BC reversed immunosuppression and completely abrogated tumor progression in combination with anti-PD-1 antibodies, suggesting a pro-tumor role of AIM2 in BC." (PMID 40002808, 2025). "Second, the expression levels and mechanisms of AIM2 action can vary substantially across different tumor types and individual patients." (PMID 39744568, 2025). "AIM2 has the capacity to impede tumor progression through the facilitation of apoptosis, suppression of cell proliferation, and initiation of autophagy." (PMID 39744568, 2025). "In support, the double knock down of STING/AIM2 in a mouse model of GBM, eliminated the tumor immune-suppression effects caused by TTFields." (PMID 39857785, 2025). "In terms of patterns among inflammasome components, NLRP3 predominantly exhibits pro-tumor effects across multiple cancers, whereas AIM2 largely shows anti-tumor activity." (PMID 41291696, 2025). "These approaches significantly increase the sensitivity of tumor cells to the immune system by inhibiting the activity of AIM2 or inflammasomes, or by promoting the oncolytic effects of AIM2, thereby augmenting the anti-tumor immune response." (PMID 39744568, 2025). "Due to this property, AIM2 is commonly applied to the monitoring test of new dendritic cell vaccine and immunotherapy which can attack and destroy tumor cells." (PMID 40386782, 2025). "Studies have shown that AIM2 can promote tumor growth in KRAS-driven lung adenocarcinoma models, indicating its role in tumorigenesis independent of inflammasome activation." (PMID 40386782, 2025). "The authors also found that the basal levels of AIM2 mRNA were significantly lower in clinical tumor specimens, but higher in BPH, compared to normal prostate tissue." (PMID 40002808, 2025). "Owing to both tumor-promoting and tumor-suppressive roles, pharmacological intervention targeting AIM2 activity must be finely controlled for therapeutic purposes." (PMID 41062723, 2025). "From a perspective of tumor promotion and suppression, AIM2 exhibits diverse roles across different types of cancers." (PMID 39744568, 2025). "Particularly, self-DNA and cytoplasmic double-stranded DNA (dsDNA) released by cancer cells, byproducts of genomic instability, were reported to trigger the cytosolic absent in melanoma 2 (AIM2) promoting tumor growth." (PMID 40002808, 2025). "In hypopharyngeal squamous cell carcinoma, for instance, the expression of AIM2 in tumor tissues was significantly lower than that in adjacent normal hypopharyngeal tissues." (PMID 40386782, 2025). "Reports on the role of AIM2 in GC have yielded mixed results and we will delve into its tumor-suppressing effects." (PMID 40386782, 2025). "The activation of the AIM2 inflammasome by viral stimuli and elements within tumor microenvironment (TME) facilitates the secretion of IL-1β." (PMID 40386782, 2025). "Recent studies have highlighted AIM2’s potential as a tumor suppressor, demonstrating its involvement in regulating various cellular processes that are crucial for tumor progression and metastasis." (PMID 40386782, 2025). "In fact, AIM2, NLRP3 and RIG-1 were overexpressed in EBV-associated NPC and were interestingly reported to possess anti-tumour effects in EBV-associated NPC via IL-1β release." (PMID 41440367, 2025).
tumor (continued). "In summary, AIM2 demonstrates potential anti-tumor properties in BC through the inhibition of cell proliferation and the facilitation of apoptosis or pyroptosis." (PMID 39744568, 2025). "AIM2 has been demonstrated significant potential as a therapeutic target for tumor treatment, particularly in “cold tumors” where conventional immunotherapy proves ineffective." (PMID 39744568, 2025). "Focusing on the AIM2 inflammasome, it was found that AIM2 expression suppressed the proliferation and tumorigenicity inducing tumor cells toward apoptosis." (PMID 40002808, 2025). "AIM2 is essential for producing IL-1β and IL-18 that encourage the accumulation of Treg cells and tumor progression in vivo." (PMID 41291696, 2025). "As anticipated above, it was observed that the deletion of the AIM2 gene using the CRISPR-Cas9 system significantly reduced tumor cell proliferation and temozolomide resistance in vitro." (PMID 40002808, 2025). "AIM2 has been shown to exert anti-tumor effects by inhibiting cancer cell proliferation, inducing apoptosis, pyroptosis, and enhancing the immune response against cancer cells by modulating TAMs and TANs." (PMID 39744568, 2025). "This duality reinforces AIM2’s status as both a driver of chronic inflammation-related tumorigenesis and a facilitator of beneficial immune activation, depending on tumor context and therapeutic strategy." (PMID 41291696, 2025). "Furthermore, AIM2 has been demonstrated to facilitate the transition of tumor-associated macrophages (TAMs) from an anti-inflammatory M2-type to a pro-inflammatory M1-type by activating inflammasome signaling, thereby promoting tumor rejection and impeding tumor cell proliferation." (PMID 39744568, 2025). "This indicates that AIM2 not only plays a role in tumor suppression but also in shaping the immune landscape of CRC, making it a promising target for immunotherapy approaches." (PMID 40386782, 2025). "The authors showed that a higher expression of AIM2 in tumor tissues was correlated to the poor prognosis of patients and that AIM2 upregulation reinforced the transcriptional regulatory activity of STAT1/NF-κB towards the PD-L1 gene." (PMID 40002808, 2025). "Very recently, luteolin, a natural flavonoid well known for its anti-inflammatory properties was reported as being able to mediate the anti-tumor effect in NSCLC in an AIM2-dependent manner." (PMID 40002808, 2025). "AIM2 has been identified as a potential biomarker for predicting tumor progression and patient outcomes in various SCC types." (PMID 40386782, 2025). "PTX treatment significantly increased inflammasome activation, as indicated by significantly increased NLRP3, ASC, NOD2 and AIM2 (p < 0.0001) expression in MDA-MB-231 tumor cells compared to control cells." (PMID 39433537, 2024). "This study suggested that AIM2 inflammasome affected M2 macrophages polarization within the tumor microenvironment." (PMID 39222064, 2024). "AIM2 can activate the hepatic inflammasome, release inflammatory factors, and induce tumor cell pyroptosis." (PMID 39222064, 2024). "AIM2 upregulation due to promoter hypomethylation has been shown to play an oncogenic role and the enforced expression of AIM2 promoted tumor growth and lymph node metastasis in OSCC." (PMID 38166970, 2024). "Over the years, studies on AIM2 showed its role as a tumor suppressor, showing that a reduced expression of the AIM2 gene was correlated with cancer progression and poor prognosis in CRC." (PMID 39684769, 2024). "H&E staining results showed extensive nuclear condensation and cytoplasmic rarefaction in tumor tissues from the AIM2 overexpression group, along with a decreased Ki67 expression." (PMID 39222064, 2024). "Beyond its immune regulatory function, study has demonstrated that AIM2 also exerts substantial influence in tumor biology." (PMID 39222064, 2024).
tumor (continued). "AIM2 displayed antitumor activity in tumor cells, and within HCC cells, the expression of Caspase‐1 and the concentrations of IL‐1β and IL‐18 were positively correlated with AIM2 expression." (PMID 39222064, 2024). "This reduction in AIM2 was strongly associated with higher serum AFP levels, vascular infiltration, poor tumor differentiation, incomplete tumor envelope, and unfavorable odds of survival after surgery." (PMID 39450183, 2024). "Recent studies have shown that AIM2 is highly expressed in ccRCC and promotes tumour development through immune activation pathways." (PMID 38103146, 2024). "Based on these results, we conclude that elevated expression of DNASE1L3 and AIM2 improve the efficacy of sorafenib in conjunction with PD-1 mAb therapy, resulting in significant tumor growth inhibition and extended survival in mice." (PMID 39479454, 2024). "The AIM2 gene has been described as a tumour suppressor in early studies but in NSCLC it appears to promote tumour growth as an oncogene in an inflammasome-dependent way." (PMID 38168015, 2024). "After NLRP3-specific inhibitor MCC950 was added, the levels of NLRP3, ASC, NOD2 and AIM2 statistically decreased (p < 0.001 and p < 0.0001) upon stimulation with LPS and ATP of tumor cells." (PMID 39433537, 2024). "This review article addresses recent progress in elucidating the cell-specific functions of AIM2 within inflammatory and tumor environments." (PMID 39600708, 2024). "AIM2 can regulate tumor development or host defense by inhibiting the Akt signaling pathway independent of inflammasome, while Akt phosphorylation has been shown to attenuate apoptosis." (PMID 38918243, 2024). "cGAS and AIM2 are CDSs that are activated in the presence of cytosolic dsDNA and are expressed in various cell types, including immune and tumor cells." (PMID 37046775, 2023). "AIM2 accelerated tumor development by reducing CD4+ effector T cells while increasing the number of Treg cells." (PMID 37752941, 2023). "This review summarizes current research on the mechanisms underlying CDSs, absent in melanoma 2 (AIM2), cyclic GMP-AMP synthase (cGAS), and stimulator of interferon genes (STING)—downstream signaling effectors of cGAS—in the tumor microenvironment." (PMID 37046775, 2023). "In a subsequent analysis, IHC examination revealed an inverse correlation between Ki67 expression levels and AIM2 in the mice's orthotopic tumor tissues." (PMID 37932362, 2023). "Absent in melanoma 2 (AIM2) was initially discovered as an interferon-induced tumor suppressor but was later identified as a cytoplasmic double-stranded DNA (dsDNA) sensor that can assemble inflammasomes with ASC and procaspase-1." (PMID 38203518, 2023). "On the other hand, NLRP3 in DCs and AIM2 in macrophages have been shown to facilitate anti-tumor immunity." (PMID 36932407, 2023). "IL-1β enhances tumor cell proliferation, migration and invasion while coculture of tumor cells with macrophages enhances the proliferation of tumor cells, which is AIM2 and caspase 1/11 dependent." (PMID 37449203, 2023). "The inflammasome inhibitor, Ac-YVAD-CMK abrogates M1 polarization, while overexpression of AIM2 in macrophages inhibits tumor growth and metastasis." (PMID 36932407, 2023). "This review summarizes the current research on the roles of cGAS, STING, and AIM2 in immune cells and tumor cells in the tumor microenvironment and discusses the future prospects of anti-tumor treatment approaches based on these molecules." (PMID 37046775, 2023). "AIM2 was initially classified as a tumor suppressor target; however, it has been discovered that AIM2 also plays a role in renal inflammation and fibrosis." (PMID 37500614, 2023). "We identified AIM2 as a specific prognostic gene through Cox analysis and found that AIM2 was overexpressed in tumor samples compared to normal samples." (PMID 37932362, 2023).
tumor (continued). "Recent studies have shown that the expression of NLRP3, AIM2 and caspase-1 was significantly increased in tumor specimens from melanoma patients who had been effectively treated with PD-1." (PMID 37497237, 2023). "Transcriptomically, AIM2 was overexpressed in tumor tissues in the TCGA-KIRC project and oncomine database." (PMID 36923928, 2023). "SLC25A37 mediated by the PINK1-PARK2 pathway increases mitochondrial iron accumulation, which leads to the HIF1A-dependent Warburg effect and AIM2-dependent inflammasome activation in tumor cells." (PMID 36937929, 2023). "Recent studies have revealed that AIM2 activity induces pro-tumor growth through multiple parallel pathways, including inhibition of STING-type I IFN signaling." (PMID 37046775, 2023). "IL-1β and coculture of tumor cells with macrophages enhances the proliferation of tumor cells which is AIM2 and caspase 1/11 dependent (Gigure 6)." (PMID 37449203, 2023). "Initially, AIM2 was identified as a tumor suppressor for hepatocellular carcinoma, melanoma, and HPV-infected cervical carcinoma." (PMID 37500614, 2023). "Small animal live imaging indicated that AIM2 overexpression considerably promoted the level of tumor metastasis." (PMID 36923928, 2023). "Macrophages release IL-1β indicative of inflammasome activation after stimulation with LPS and tumor-CM, which is AIM2 dependent." (PMID 37449203, 2023). "This led to the observation that mice receiving sh-AIM2 injections displayed increased tumor weight at the experiment's conclusion, as compared to the sh-NC group." (PMID 37932362, 2023). "While the length of dsDNA in the tumor cells we used (A549, Hela, MCF-7) remains elucidated, it is certainly possible that the dsDNA present in these tumor cells is too short to trigger AIM2 activation in this model." (PMID 37449203, 2023). "IL-1β and coculture of tumor cells with macrophages enhances the proliferation of tumor cells which is AIM2 and Casp1/11 dependent." (PMID 37449203, 2023). "shown that AIM2 inhibits tumor cell proliferation by suppressing AKT phosphorylation in colonic epithelial cells and colon cancer cells, does not affect body inflammation and inflammasomes activation." (PMID 36742336, 2023). "AIM2, a double-strand DNA sensor in the inflammasome of pyroptosis, was also found to be upregulated in the tumor samples of this work, which indicated active pyroptosis in BC tissue." (PMID 37511974, 2023). "Our study proposes a mechanism that AIM2 suppresses tumor progression and suggests AIM2 inflammasome activation during BCG treatment is a potential strategy for patients with BLCA." (PMID 36386141, 2022). "Subsequent in vivo experimental models showed that the enhanced survival noted for animals implanted with TTFields-treated wild-type (WT) tumor cells was abrogated when mice were challenged with TTFields-treated STING/AIM2-double-knockdown tumor cells." (PMID 35426370, 2022). "In their study, RT damaged tumor cell DNA, activated AIM2, and subsequently induced caspase-1-GSDMD pathway-mediated pyroptosis, and reduced tumor volume and weight." (PMID 36457125, 2022). "scRNA-seq analysis suggested that AIM2 inflammasomes differ significantly among different cells in the tumor microenvironment." (PMID 36248785, 2022). "In contrast, AIM2 inflammasomes scores were only detected in KIRC with elevated scores in the late tumor stages." (PMID 36248785, 2022). "The AIM2 inflammasomes score was significantly and positively correlated with the tumor immunity score and the stroma score." (PMID 36248785, 2022). "In another study, it was shown that AIM2 overexpression augmented the tumor load of human GC cell line xenografts by interacting with EB1 to promote epithelial cell migration and tumorigenesis, which was independent of inflammasome activity and inflammation." (PMID 36120327, 2022). "In the precancerous stage of HPV-infected cells, AIM2 plays a tumor suppressor role by activating caspase-1 to promote pyroptosis of tumor cells." (PMID 36497244, 2022).